AIMP2 (aminoacyl tRNA synthetase complex interacting multifunctional protein 2)
Diseases named in the same sentence as AIMP2 in open-access papers (continued):
Sharing a sentence is not in itself a finding about the gene and the disease.
AIMP2 also shares sentences with these, for which no sentence is quoted: neurodevelopmental disorder (3 papers); adenoma (1); anemia (1); autism (1); Baraitser-Winter syndrome 1 (1); cerebellar ataxia (1); cervical carcinoma (1); colon carcinoma (1); enterovirus infections (1); head and neck squamous cell carcinoma (1); hypogonadotropic hypogonadism (1); liver cancer (1); lung adenocarcinoma (1); Lynch syndrome (1); melanoma (1); Mental retardation, autosomal dominant 48 (1); microcephaly (1); osteogenesis imperfecta (1); Parkinsonism (1); prostate adenocarcinoma (1); trigeminal neuralgia (1).